EGFR (epidermal growth factor receptor)
Diseases named in the same sentence as EGFR in open-access papers (continued):
Sharing a sentence is not in itself a finding about the gene and the disease.
breast carcinoma (continued). "We recently extended this finding and found that EGCG inhibits the activation of EGFR, HER2, and HER3, and their multiple downstream signaling pathways in human HNSCC, breast cancer, and colon cancer cell lines." (PMID 19325845, 2008). "We also characterized EGFR's influence on S100A7 expression and its role in the EGF-induced metastasis and invasion of breast cancer cells." (PMID 18320059, 2008). "In the present study, we investigated the activation of the NF-κB transcription factor in breast cancer in terms of ER signalling and the hyperactivation of MAPK due to EGFR and/or ErbB2 overexpression, with special emphasis on the IBC phenotype." (PMID 17700572, 2007). "This study shows that, in a number of breast cancer patients, serum levels of the oncogenes HER2 and EGFR change significantly between primary diagnosis and the onset of metastatic disease, albeit in opposite directions." (PMID 17976236, 2007). "LG2 markers include 190 genes, among which are many oncogenes, (BCL2 (down, breast cancer poor prognosis marker), RAD51 (up), EGFR (up), RUNX3 (up), BCL9 (down) and VAV3 (down) and tumor suppressor gene NME1 (up)." (PMID 17683614, 2007). "We show here that, in addition to activating the canonical Wnt/β-catenin pathway, Wnt1 transactivates EGFR and stimulates ERK1/2 activity in many human breast cancer cells." (PMID 17897439, 2007). "Our data show that interference with autocrine WNT signaling in human breast cancer reduces proliferation and survival of human breast cancer cells and rescues ER+ tumor cells from 4-HT by activation of the canonical WNT pathway and EGFR transactivation." (PMID 17897439, 2007). "To explore the possibility that Wnt signaling is de-regulated in breast cancer by autocrine pathway activation, we examined breast cancer cell lines for signs of canonical pathway activity and for crosstalk between WNT, EGFR, and ERK1/2 signalling." (PMID 17897439, 2007). "In summary, the results suggest that, in the examined breast cancer cell lines, WNT activity contributes to autocrine EGFR activation and ERK1/2 activity." (PMID 17897439, 2007). "Our findings suggests that CK5/6 and/or EGFR expressing tumor types have a persistently poorer prognosis over the longer term, an observation that may have important therapeutic implications as drugs that target the EGFR are currently being evaluated in breast cancer." (PMID 17650314, 2007). "The EGFR antagonist also diminished steroid and growth factor induced Raf phosphorylation in both SKBR3 and MCF-7 breast cancer cell lines." (PMID 16805920, 2006). "In a recent study of breast cancer patients, 35% of 306 HER2-overexpressing tumours were found to express EGFR Conversely, 87% of EGFR-overexpressing tumours were found to overexpress HER2 as well." (PMID 16622439, 2006). "Blocking EGFR signaling (using gefitinib) reduces active MAPK and inhibits proliferation of tamoxifen resistant breast cancer cells, while the MAPK inhibitor, U0126, partially restores tamoxifen sensitivity." (PMID 16926831, 2006). "To investigate the potential role of HER2 as a predictive marker for responsiveness to EGFR targeted therapies, we developed a series of MCF7 breast cancer cell line subclones that express graded levels of HER2." (PMID 16622439, 2006). "Human epidermal growth factor receptor 2 (HER2), a member of the epidermal growth factor receptor (EGFR) family of tyrosine kinases, is overexpressed in 25–30% of human breast cancers." (PMID 16622439, 2006). "Gefitinib (Iressa, ZD 1839, AstraZeneca) blocks the tyrosine kinase activity of the epidermal growth factor receptor (EGFR) and inhibits proliferation of several human cancer cell types including breast cancer." (PMID 15987464, 2005). "Because EGFR/ERBB1 and ERBB2 are important and frequently overexpressed breast cancer genes, it is unlikely that LRIG1, as an ERBB antagonist, is a tumour promoter." (PMID 16168117, 2005).
breast carcinoma (continued). "AG1024 (an inhibitor of IGF-1R) was used with gefitinib for treatment of MDA468, MDA231, SK-BR-3, and MCF-7 breast cancer lines, which express similar levels of IGF-1R but varying levels of EGFR." (PMID 15987464, 2005). "A high expression level of epidermal growth factor receptor (EGFR)/HER1 has been suggested to lead to a shorter survival time and resistance to endocrine therapy in patients with breast cancer." (PMID 14710235, 2004). "Expression of EGFR, HER2 and phosphorylated ERK1/2 were measured by immunoblotting in a panel of breast cancer cell lines." (PMID 15280923, 2004). "Gefitinib suppressed the EGFR transactivation by IGFR, and thereby induced apoptosis in breast cancer cells." (PMID 14583782, 2003). "Twenty-two samples of female human breast cancer tissue that exhibited positivity for ER and EGFR by ER-ICA using the H222 monoclonal antibody and EGFR-ICA using the EGFR1 monoclonal antibody underwent the dual ICA." (PMID 8198966, 1994). "The results of this study suggest that c-erbB-2 protein overexpression, a marker of poor prognosis in breast cancer, is associated with a lack of response to endocrine therapy on relapse, and particularly in combination with EGFR may be useful in directing therapeutic choices." (PMID 1346366, 1992). "In breast cancer, STAT3 activation via EGFR signaling promotes SOX2 expression." (PMID 41511366, 2026). "EGFR amplification occurs in ~1–5% of breast cancer patients with worse outcomes compared to patients without EGFR amplification." (PMID 41291067, 2026). "Despite these data, clinical trials investigating EGFR inhibitors have not shown great promise in breast cancer, with studies finding partial response rates of 0–6%." (PMID 41291067, 2026). "The peptide-functionalized cubosomes exhibited selective uptake of up to 75% in EGFR-overexpressing MDA-MB-468 breast cancer cells while showing minimal uptake (9%) in EGFR-negative HEK-293 cells." (PMID 41710968, 2026). "To evaluate cell-type-specific delivery of mRNA-LNPs pre-mixed with BsAbs, we used MDA-MB-468 breast cancer cells, which express EGFR but not PSMA, and LNCaP prostate cancer cells, which express both EGFR and PSMA." (PMID 40235853, 2025). "The GPER/EGFR/ERK pathway enhances β1-integrin expression, accelerating CAF-induced epithelial-to-mesenchymal transition (EMT) and leading to resistance to tamoxifen in breast cancer cells." (PMID 40843360, 2025). "In a study on breast cancer cells exhibiting MDR, targeted liposomes loaded with doxorubicin and functionalized with anti-EGFR (epidermal growth factor receptor) antibodies were able to overcome resistance and showed enhanced cellular uptake and cytotoxicity compared to non-targeted formulations." (PMID 41011159, 2025). "Although EGFR is an important molecular target, the results of clinical trials of EGFR-targeted therapies in breast cancer have not been satisfactory." (PMID 41026783, 2025). "Therefore, through its effects on cancer signaling pathways, including the GPER and EGFR/ERK pathways, BPA can increase apoptosis and gene expression, thereby promoting cell viability and proliferation in breast cancer cell lines." (PMID 41440754, 2025). "Conversely, ADAMTS6 inhibits EGFR activation without altering its expression in breast cancer cells." (PMID 41465277, 2025). "EVsderived from breast cancer cells contain elevated levels of proteinssuch as HER2, EGFR, CA 125, CA15–3, PSMA, EpCAM, and MUC1,which are commonly found in breast cancer patients and may serve asEV-derived biomarkers." (PMID 40720603, 2025). "Therefore, the combination of EGFR and PI3K pathway inhibitors should be tested in breast cancer patients with EGFR amplification and PI3K pathway alteration." (PMID 40501689, 2025).
breast carcinoma (continued). "Proof-of-concept studies reveal that EGFR and HER2 FolTAC-dual effectively counteracts resistance in Trastuzumab/Lapatinib-resistant HER2-positive breast cancer models, while PD-L1 and VISTA FolTAC-dual rejuvenates immune responses in PD-L1 antibody-resistant syngeneic mouse models." (PMID 41038820, 2025). "EGFR/Her2 heterodimers play a key role in modulation of Tzm effects in Her2+ cell lines SK-BR3 and BT474, while Her2/Axl heterodimerization is responsible for trastuzumab resistance in Her2+ breast cancer cell lines." (PMID 41471069, 2025). "The review further explores non-RTK-driven resistance mechanisms in breast cancer, including EGFR activation through EGF-related ligands, nuclear localization of EGFR, and the overexpression of resistance-conferring proteins." (PMID 40560045, 2025). "We demonstrated that the omega-10 fatty acids were able to modulate the expression and activation of EGFR receptor (epidermal growth factor receptor), AKT (protein kinase B), and mTOR (mammalian target of rapamycin) signaling pathway in MCF-7, MDA-MB-231, and BT-20 breast cancer cell lines." (PMID 40943166, 2025). "Therefore, the development of novel small-molecule inhibitors capable of effectively targeting EGFR-driven NSCLC and breast cancer remains a critical area of research." (PMID 40806193, 2025). "Although studies have investigated dual EGFR/PI3K inhibition in breast cancer, they have not determined biomarkers which predict success." (PMID 40501689, 2025). "Gene expression analysis showed that GPNMB+ cells significantly upregulated genes involved in invasion and/or tissue remodeling, including EGFR, a direct interactor of GPNMB in breast cancer cells, its downstream targets (STAT3, MMP 2-3-9) and ITGB4, TGFβ, VEGF and VCAM." (PMID 40528051, 2025). "Similar EMT activation has been observed in HER2-amplified breast cancer cells treated with lapatinib, basal-like breast cancer cells exposed to PI3K/mTOR inhibitors, and paclitaxel-resistant lung or prostate cancer cells tolerating EGFR-TKIs58–60." (PMID 40738896, 2025). "The coexpression of EGFR (epidermal growth factor receptor) and HER2 in luminal breast cancer is particularly striking, and the combination of HER2 and EGFR blockade has a synergistic effect on tumor lysis because of the ability to overcome compensation via other pathways." (PMID 41348261, 2025). "CAR T-cell therapy in breast cancer has shown early promise, particularly in HER2-positive breast cancer, with several clinical trials underway that target different antigens such as mesothelin, EGFR, and folate receptor-alpha." (PMID 40940995, 2025). "Receptor tyrosine kinases (RTKs), including EGFR, VEGFR, PDGFR, and FGFR, regulate key processes such as proliferation, angiogenesis, and metastasis in cancers like non-small cell lung cancer (NSCLC), colorectal cancer (CRC), and breast cancer." (PMID 39860039, 2025). "FDA-approved MABS are now in clinical use in multiple cancer indications, such asrituximab (anti-CD20) for CLL, cetuximab (anti-EGFR) for EGFR+ colorectal cancer, trastuzumab (anti-HER2) for HER2+ breast cancer, and elotuzumab (anti-SLAMF7) for multiple myeloma." (PMID 40561796, 2025). "In addition, hsa-miR-7-5p has been shown to act as a tumor suppressor in breast cancer, including TNBC, where it inhibits cell proliferation and migration by targeting oncogenes such as EGFR and IRS1." (PMID 40867247, 2025). "Interestingly, lapatinib, an EGFR and HER2+ receptor inhibitor, is broadly used for treatment of HER2+ advanced breast cancer patients." (PMID 40612670, 2025).
breast carcinoma (continued). "In breast cancer cells, PTPN9 directly dephosphorylates EGFR and ErbB2, attenuating downstream STAT3/STAT5 signaling, suggesting that PTPN9 status could influence responses to EGFR-directed TKIs." (PMID 41275311, 2025). "Thus, we used MMTV-TGF-α breast cancer mouse model which overexpress human TGF-α, a part of the epidermal growth factor receptor (EGFR)/Erb cascade that play a key role in MT development." (PMID 40986521, 2025). "Additionally, in the realm of CAR-T and CAR-NK therapy for breast cancer, several targets, such as EpCAM (NCT02915445), VEGFR (NCT05477927), EGFR, and B7-H3 (NCT05341492), have been explored in clinical trials." (PMID 41573636, 2025). "Exosomes from breast cancer cells (MCF-7) and normal mammalian epithelial cells (MCF-10A) were collected and Western blotting was used to detect EpCAM, PSMA, HER2, EGFR, CEA, and CA125, and a marked increase in expression of EGFR, CEA, and CA125 was observed in MCF-7." (PMID 40075875, 2025). "The validated breast cancer surface marker panel consisted of MUC1, EGFR, and EpCAM." (PMID 41404198, 2025). "ER+ breast cancer cells were incubated with or without E2-containing media for 24 h to investigate the effect of E2-induced AREG on the EGFR signaling pathway." (PMID 40422206, 2025). "EGFR amplification occurs in approximately 1-5% of breast cancer patients with worse outcomes compared to patients without EGFR amplification." (PMID 40501689, 2025). "In preclinical models of HER2-positive breast cancer, entinostat exhibited combinational synergistic effects with the HER2/epidermal growth factor receptor (EGFR) dual tyrosine kinase inhibitor to inhibit tumor progression, sensitizing tumor cells to anti-HER2 treatments." (PMID 40165290, 2025). "Additionally, in claudin-low breast cancer cells, ADAM12 was shown to maintain the cancer stem cell (CSC) phenotype through the modulation of EGFR signalling." (PMID 40427200, 2025). "Since a clinical application of NIR-PIT would be relatively easy for breast cancers, and MCF-7 would be a good model for cancer that can be treated with EpCAM-NIR-PIT but cannot be treated with EGFR-NIR-PIT, we used MCF-7 breast cancer as a model of EpCAM-targeted NIR-PIT in vivo." (PMID 40792441, 2025). "The identification of EGFR in 1978 and HER2 in 1984, along with the recognition of HER2 overexpression as a negative prognostic factor, facilitated the development of targeted therapies that have transformed breast cancer management." (PMID 41228310, 2025). "Notably, ALIX has been reported to regulate both epidermal growth factor receptor (EGFR) activity and PD-L1 surface presentation in basal-like breast cancer (BLBC) cells." (PMID 41441336, 2025). "Even though EGFR expression was downregulated in both breast cancer lines and one bladder cancer cell line (data not shown), EGFR activity is traditionally determined by its state of phosphorylation at specific tyrosine residues." (PMID 40754248, 2025). "Notably, genes such as SCIN and EGFR, already known to be involved in HER2-positive breast cancer, were confirmed, reinforcing the validity of our approach." (PMID 40946111, 2025). "Among them, ATF-2 demonstrated antiproliferative activity comparable to HER2 inhibitor lapatinib and significantly suppressed HER2 expression and activity, epidermal growth factor receptor (EGFR) activity, and cyclin-dependent kinase 6 (CDK6) expression in HCC1954 breast cancer cells." (PMID 41537091, 2025). "Similar to these findings with ALK+ NSCLC cells, it is reported that in DTP cells in EGFR+ NSCLC, HER2+ breast cancer, and BRAF+ melanoma, the gene signatures of ROS production are increased after treatment with clinically relevant TKIs and the expression of antioxidant genes is also decreased." (PMID 39369284, 2025).
breast carcinoma (continued). "As another example, in the context of breast cancer, circRNA cerebellar degeneration-related protein 1 gene (CDR1) antisense RNA (CDR1as) was correlated with tamoxifen resistance through modulation of the miR-7/EGFR pathway." (PMID 41281941, 2025). "For example, while FolTAC-dual effectively targets EGFR and HER2 in resistant HER2+ breast cancer, compensatory signaling through other tyrosine kinases or pathways, such as MET or IGF-1R, may emerge over time." (PMID 41038820, 2025). "Therefore, it is reasonable to examine the effects of EGFR and IGF-IR on cancer cell proliferation, considering the important role of these RTKs in breast cancer." (PMID 40867236, 2025). "Interestingly, the canine mammary tumor (CMT)-U27 cell line showed high basal Wnt activity and high levels of EGFR, HER2, and HER3 mRNA expression, similar to HER2-overexpressing human luminal cell lines." (PMID 40563676, 2025). "In breast cancer, it has been described that KP10 can stimulate the migration and invasion of ERα-negative breast cancer cells via transactivation of the EGFR pathway and increased MMP-9 activity." (PMID 39199311, 2024). "Additionally, hydroxytyrosol has demonstrated other effects, such as reducing epidermal growth factor receptor (EGFR) levels in colon cancer cells and affecting the WNT pathway in breast cancer models." (PMID 38732529, 2024). "Our study highlights that TSL selectively inhibits the proliferation of ER+ or HER2+/EGFR+ breast cancer cell lines, but not other cancer or normal cells." (PMID 39906392, 2024). "Subsequently, DTP cells have been identified in various experimental models after targeted therapy, including additional EGFR‐mutant NSCLC cell lines, MET‐amplified gastric cancer, BRAF‐mutant melanoma, prostate cancer, colorectal cancer, and HER2‐positive breast cancer." (PMID 39184861, 2024). "Based on these findings, we hypothesised that ORes exert their effects by inhibiting EGFR, thereby modulating the PI3K-AKT pathway, suppressing GPX4 activity, and inducing ferroptosis in breast cancer cells." (PMID 39881871, 2024). "There was a non-significant difference between the ESR1 and EGFR expression levels in any breast cancer subtype." (PMID 39202273, 2024). "Advanced scRNA-seq and spatial molecular profiling in tumor specimens supported EGFR expression and higher expression of CDK2/cyclin E in TNBC compared with other breast cancer types across primary and post-NAC-resistant TNBCs, and higher levels of co-expression and spatial colocalization in TNBCs." (PMID 38772416, 2024). "Positive EGFR status has long been recognised as a negative prognostic factor in breast cancer, and evidence has pointed out that EGFR is overexpressed in triple-negative cancer." (PMID 39598379, 2024). "We investigated whether EGFR may be a potential target for ADC therapy by interrogating gene expression in 6,173 primary tumors from five breast cancer datasets." (PMID 38772416, 2024). "Though calycosin can decrease the phosphorylation levels of SRC, EGFR, ERK1/2, and Akt in breast cancer lines and meningitis, its role in chondrocytes remains unclear." (PMID 38254101, 2024). "As a result, the lack of predictive biomarkers of a response to anti-EGFR therapies in TNBC has hampered the translation of EGFR inhibitors in breast cancer." (PMID 38605363, 2024). "Patritumab deruxtecan (HER3-DXd; U3-1402) is the HER3-targeting ADC in clinical development and shown clinical benefit in breast cancer and NSCLC patients with or without EGFR mutations." (PMID 38632563, 2024). "Another study found that TGF-β-induced EMT in a breast cancer cell model alters the response to EGF, leading to increased invasiveness and metastatic potential, which is characterized by changes in cell morphology, EGFR activation, and dependency on FAK." (PMID 38926762, 2024).